IL10 (interleukin 10)
Diseases named in the same sentence as IL10 in open-access papers (continued):
Sharing a sentence is not in itself a finding about the gene and the disease.
asthma (continued). "Similar to the SLSJ study, some SNPs in the IL10 and CYP24A1 genes were modestly associated with asthma or atopy." (PMID 19852851, 2009). "SNPs located in five genes, including IL10, CYP24A1, IL1RL1, CYP2R1 and CD86, showed modest association with asthma or atopy in an asthma family study derived from the Saguenay_Lac-Saint-Jean population." (PMID 19852851, 2009). "The gene for IL-10, which is essential for the eosinophilic inflammation seen in asthma (and in this mouse model), is down-regulated, resulting in decreases in mucus production and eosinophilic inflammation without decreased IgE or IL-4." (PMID 18087596, 2007). "Collectively, these data suggests that immunosuppressive cytokines, such as TGF-β and IL-10, as well as Th1-related IL-12, can alleviate the symptom of airway inflammation in a murine model of asthma." (PMID 16677403, 2006). "Further, we have examined varying doses of IL-10 gene plasmid to test the therapeutic efficiency of this asthma animal model." (PMID 16677403, 2006). "We next decided to investigate the relative efficacy of varying doses of IL-10 gene plasmid for the alleviating effect of the severity of asthma symptom." (PMID 16677403, 2006). "At least one positive SNP with a TDT of p < 0.05 for asthma or total IgE and calcidiol or calcitriol was seen in IL10, GC, IL12B, CYP2R1, IL4R, and CYP24A1." (PMID 16600026, 2006). "Our data demonstrated that anti- inflammatory cytokines, particularly IL-10, have the therapeutic potential for the alleviation of airway inflammation in murine model of asthma." (PMID 16677403, 2006). "In humans, relative underproduction of IL-10 by alveolar macrophages and in the sputum of patients with asthma has been reported, which suggests an essential role IL-10 in regulating airway inflammation." (PMID 16677403, 2006). "Some studies found a higher IL-10 expression in subjects with asthma than in control subjects, whereas others found lower IL-10 levels." (PMID 16597326, 2006). "Our findings of a regulatory role for IL-10 in asthma are strongly consistent with the idea that IL-10 production mediates Ag-specific tolerance that protects against allergic diseases and airway inflammation." (PMID 16677403, 2006). "Here, we demonstrated, in a mouse model of allergic airway inflammation, that treatment with allergen-loaded Mφ suppress asthma manifestations in an IL-10-dependent manner." (PMID 15538945, 2004). "By using CD4+ T lymphocytes, ex vivo transduced to express IL-10, it was shown that allergen-specific lymphocytes can suppress allergen-induced asthma manifestations via production of IL-10." (PMID 15538945, 2004). "In agreement with our study, these studies indicate a pivotal role for IL-10 in limiting allergen-induced asthma manifestations." (PMID 15538945, 2004). "In the past, IL-10 has been shown to suppress allergen-induced airway manifestations of asthma in the mouse." (PMID 15538945, 2004). "Additionally, CD83cKO mice secreted elevated IL‐10, an anti‐inflammatory cytokine that also can enhance Th2 responses in a house dust mite‐driven asthma model." (PMID 39955650, 2025). "The mechanistic basis for failure to induce IL-10 production in the CD4+ T cells of individuals with asthma may be attributable to the favored expression of the cytoplasmic (cyt) tail isoform of CD46." (PMID 40309766, 2025). "However, the levels of IFN-γ, IL-10, and type-2 cytokines, including IL-4, IL-5, and IL-13, were not significantly different between Sema3E KO and WT mice in the type-2 low asthma model." (PMID 40512736, 2025). "The beneficial effects of steroids and anti-leukotrienes in asthma could be due to their ability to increase serum IL-10 levels." (PMID 40630332, 2025). "For example, in asthma, let-7 may exacerbate Th2-driven inflammation by targeting IL-10, whereas in pulmonary fibrosis, let-7d inhibits epithelial-to-mesenchymal transition and may act protectively." (PMID 41009372, 2025).
asthma (continued). "Similarly, in GSE110147, genes between the different groups (IPF/Control) were significantly enriched in interleukin-10 signalling, asthma, cytokines and inflammatory response, SARS-CoV infections, and other pathways." (PMID 40642530, 2025). "The present study showed that children with comorbid asthma and obesity/overweight had higher IL-6, TNF-α, and leptin, and lower 25-(OH) D3, IL-10, and IL-13 than children with asthma alone, and had lower IL-10 and higher IL-6, IL-13, and leptin than children with obesity/overweight alone." (PMID 40083433, 2025). "IL-10 gene expression was previously reported to be reduced in people with asthma." (PMID 41256924, 2025). "IL-10 in asthma works by limiting Th2 allergic inflammation and neutrophilic inflammation." (PMID 39861052, 2025). "The comorbid asthma and overweight/obesity group had a lower expression of IL-10 and IL-13 than children with asthma alone, suggesting that the expression of Th2-related inflammatory factors was higher in children with asthma but not in children with comorbidity." (PMID 40083433, 2025). "Our research revealed that M2 macrophages promote IL-10+ B cells in asthma." (PMID 40342727, 2025). "When we tested for nutrients associated with proinflammatory cytokines, FAs showed the most prominent negative associations with IL-2, IL-10, IL-13, and IL-17A, which play key roles in the inflammatory processes underlying asthma." (PMID 41256924, 2025). "Therefore, this study aims to investigate the mechanisms linking ICOS signaling to IL-10 production in ILC2s in murine allergic models, with the goal of uncovering new targets for the treatment of severe asthma and other ILC2-mediated inflammatory conditions." (PMID 40627441, 2025). "Because HBOT increases IL-10 and reduces oxidative stress conditions known to support Treg function, oxygen-based therapies may indirectly enhance regulatory pathways in asthma." (PMID 41515904, 2025). "In asthma, it reduces oxidative stress by metabolic switching and IL-10 production." (PMID 40002370, 2025). "The immunomodulatory property of E. granulosus infection and its cyst fluid proteins on human immune system have been demonstrated previously in the treatment of ovalbumin (OVA)-induced asthma in mice by increasing IL-10 and Tregs and down-regulating IL-5, IL-17." (PMID 39548530, 2024). "As major producers of short-chain fatty acids, Lachnospiraceae are involved in regulatory T cell development in the gut, and gut regulatory T cells, perhaps through IL-10 expression, may be protective against the development of asthma." (PMID 38326796, 2024). "Decreased levels of IL-10 have been shown in asthma and psoriasis." (PMID 39595087, 2024). "Recent studies have shown that pediatric asthma patients possess lower levels of CD24+CD38+ regulatory B cells producing IL-10 compared to a control group, highlighting the significant role of an appropriate quantity and function of regulatory B cells in controlling allergic inflammation." (PMID 39767628, 2024). "Furthermore, in some asthma endotypes, especially those with lower plasma levels of anti-inflammatory cytokines like IL-10, virus-induced exacerbations can still be a major concern even when the illness is properly controlled." (PMID 38892971, 2024). "Additionally, this analysis should include the nasal compartments, particularly regarding IL-10, as its levels in this tissue have been shown to negatively correlate with asthma onset." (PMID 39451246, 2024). "Additionally, several anti-inflammatory biomarkers, including regulatory T cells (Tregs), the antimicrobial peptide cathelicidin (LL-37), and IL-10, have also been studied in patients with asthma." (PMID 39322954, 2024). "In addition, obesity and asthma showed a significant interaction effect on the plasma levels of IL-5, IL-10, IL-17A, IL-33, TNF-α, and leptin." (PMID 39902293, 2024).
asthma (continued). "Moreover, it has been shown that asthma alters the homeostasis of Bregs: in adult as well as pediatric patients with allergic asthma, a lower percentage and absolute number of several IL-10 expressing Breg subsets are found." (PMID 38172451, 2024). "In summary, the present results demonstrate that stigmasterol have anti-inflammatory effects both locally and systemically, reduces the excessive production of Th 17 cells in the body, increases IL-10 levels and down-regulates IL-17A levels, to improve the symptoms of asthma in mice." (PMID 38579176, 2024). "Reduced levels of IL-10 in our overweight/obesity alone group indicate that obesity could act as a contributing factor for asthma development through suppression IL-10 levels." (PMID 39902293, 2024). "Asthma was associated with the increased expression of pro-inflammatory cytokines, including IL-2, IL-5, IL-13, IL-17A, IL-22, IL-33, and TNF-α, and reduced levels of anti-inflammatory cytokine, IL-10 and adipokine, leptin in the circulation." (PMID 39902293, 2024). "Thus, a positive correlation of asthma with systemic IL-10 and organoid expression of Tnf, Cxcl10, Cldn5, Cldn4 in the A group was found." (PMID 38255939, 2024). "The anti-inflammatory behavior of M2 macrophages is largely attributed to the release of IL-10, since a lack of IL-10 in macrophages contributes to the pathogenesis of asthma; moreover, supplementing with IL-10 causes less inflammation in airway." (PMID 37181813, 2023). "Furthermore, in asthmatic children undergoing AIT, a combination treatment with VD3 reduced rhinitis and asthma and further enhanced the increase in Tregs, IL-10, and TGF-β." (PMID 37371795, 2023). "Therefore, our results suggest that Asian children are better protected from pediatric asthma when IL‐10 levels are low." (PMID 37937689, 2023). "-Examining the role of hBM-MSCs-EVs paracrine effects in immune modulation that mimics paternal MSCs and hence therapeutic potential for asthma. -hBM-MSCs-EVs promote Tregs propagation and immunological suppression capacity by upregulating PBMCs cytokines IL-10 and TFG-β1 of asthmatic patient." (PMID 36679199, 2023). "IL10 is widely recognized for its crucial involvement in the pathogenesis of asthma." (PMID 37937689, 2023). "The positive impact of 1,25(OH)2D3 on Treg cells and IL-10, which help suppress Th2 responses, may be one of the reasons why vitamin D is beneficial for asthma treatment." (PMID 37760982, 2023). "We used the major databases and searched specifically for terms related to IL‐10 and asthma." (PMID 37937689, 2023). "IL-10 secreted by lung Treg cells and Tr1 cells can inhibit the production of pro-inflammatory cytokines IL-5 and IL-13, which play important roles in respiratory diseases such as asthma." (PMID 37795866, 2023). "As such, perhaps the airway hyperresponsiveness and bronchial hyperinflammation in asthma may be attributable to inadequate downregulation of immune responses due to diminished numbers of IL-10+ILC2." (PMID 37947634, 2023). "A significant association between IL10 rs1800896 polymorphism and risk of pediatric asthma was also not observed when the data were analyzed according to the dominant model (random‐effects model, OR = 1.257, 95% CI = 0.430–3.671, P = 0.676)." (PMID 37937689, 2023). "Therefore, IFN-γ, IL-17, and asthma-related targets IL-4 and IL-10 were considered inflammatory factors for the evaluation of asthma." (PMID 36636604, 2023). "Anti-IL-10 treatment diminished the ameliorating effect of methane on asthma." (PMID 35812246, 2022). "Vitamin D seems to play a role in asthma control, given its effects on immune cell function, oxidative stress, airway remodelling and corticosteroid responsiveness through various pathways, including those involving IL-10 and IL-17." (PMID 36362786, 2022).
asthma (continued). "Il-10 has been found to be a strong inhibitor of eosinophil recruitment in mucosal tissue, contributing to the protection or resolution of airway inflammation in conditions such as asthma and chronic obstructive pulmonary disease." (PMID 36143240, 2022). "Although studies revealed that SMD can attenuate asthma by regulating the expression of inflammatory mediators such as of INF-γ, IL-4, IL-10, IL-13, and TNF-α, the exact mechanism underlying its protective effect remains unclear." (PMID 36578267, 2022). "In fact, the level of Th1 cytokines IL-12 and IFN-ɣ as well level of Treg cytokine IL-10 in lung of asthma mice was lower than control, and inversely, Th2 cells response-associated the cytokines IL-4, IL-5, and IL-13 had a significant increase in lung of asthma mice compared to the control group." (PMID 36685604, 2022). "However, during the first week of life, IL-12 production is delayed and restrained by IL-10 secretion leading to an intrinsic bias to generate Th2 responses and a propensity to develop asthma." (PMID 36685549, 2022). "Corticosteroids increase the expression of IL-10 in macrophages, and this may contribute to their anti-inflammatory effects in asthma." (PMID 35608088, 2022). "MiR-146a may exacerbate the disease in asthma patients by increasing IL-1β production and miR-106a by decreasing IL-10 production." (PMID 36311189, 2022). "Furthermore, the increase in IL-10 and other anti-inflammatory cytokines in the pediatric population is related to the development of allergic diseases such as rhinitis and asthma." (PMID 36146688, 2022). "In addition, the IL-4 and IL-10 levels in the asthma group were higher than that in the pneumonia group, while the IL-12 and IFN-γ levels decreased." (PMID 36045657, 2022). "As an important anti-inflammatory cytokine, IL-10 is a promising candidate to control asthma." (PMID 36520525, 2022). "Our data provide new insight into the complexity of tissue-based regulation during a Th2 immune response and suggest that IL-10 may be an interesting candidate for therapeutic targeting in Th2 dominated diseases such as allergy, asthma and helminth infection." (PMID 35428872, 2022). "The inhibition of autophagy may also enhance IL-10 production, decreasing inflammation in patients with asthma." (PMID 35747690, 2022). "According to the prediction results of network pharmacology, IL-6, TNF, CXCL8, IL-10, IL-1β, and IL-4 may be the key targets of Danlong Dingchuan Decoction against asthma." (PMID 35186104, 2022). "Concerning pathological condition of asthma, blockage of Sema6D signal from the tissue niches might have therapeutic potential of attenuating airway type 2 inflammation by up-regulating IL-10 production from ILC2s." (PMID 36038260, 2022). "Similarly, an evaluation of the change in IL-10 expressed through CD4+ regulatory T cells in the serum shows a 60% reduction in asthma induced by OVA compared to that in normal mice." (PMID 36115955, 2022). "Future studies however are needed to assess whether regulatory B cells producing IL-10 and IL-35 could provide novel opportunities for immune regulation of lung inflammation especially during severe uncontrolled asthma." (PMID 36067164, 2022). "Also, the fact that two fragrances showed a significant upregulation in the secretion of IL-10, more studies in vivo are necessary to confirm this finding as a potential adjuvant for asthma treatment." (PMID 34046206, 2021). "The observed differences in the frequencies of Treg cell subtypes associated with the susceptibility of the animals to experimental asthma suggest that CD4+CD25+Foxp3+ and IL-10-producing CD4+ Treg cells may play different roles in asthma control." (PMID 34924814, 2021). "Similarly, the prednisolone positive control group also showed reduced levels of IL-4, IL-5, and IL-10 compared to the asthma group." (PMID 33919400, 2021).
asthma (continued). "Polymorphisms of IL-10, IL-10R, and STAT3, a Janus kinase (JAK)–signal transducer and activator of transcription, activated downstream of IL-10R were found to be associated to asthma and higher levels of IgE, without interfering with IL-10 levels." (PMID 34924814, 2021). "The depletion of γδ T cells in mice model of asthma exacerbation leads to significant decrease in BALF IL-10 level, which may suggest the important regulatory role of γδ T cells." (PMID 33661375, 2021). "Similarly, in a study carried out in an experimental model of asthma, laser was able to increase IL-10 levels." (PMID 35185864, 2021). "We quantified macrophage subsets in bronchial biopsies of asthma patients using interferon regulatory factor 5 (IRF5)/CD68 for Th1-associated macrophages, CD206/CD68 for Th2-associated macrophages and interleukin 10 (IL10)/CD68 for anti-inflammatory macrophages." (PMID 35387061, 2021). "Moreover, IL-10 displays pleiotropic effects in key inflammatory cells of asthma; for instance, it was described to have distinct roles in IgE production, either inhibiting IgE switching or potentiating IgE production on IgE isotype switched cells." (PMID 34924814, 2021). "Moreover, Th2-specific cytokines levels, including IL-4, IL-5, and IL-10, were lower in P. cocos extract-administrated groups at all doses than those in the asthma control group." (PMID 33919400, 2021). "It is of great interest to know whether AIT affects Tfh or Breg cells in relation to the levels of IL-4 and IL-10 in a murine asthma model." (PMID 34804031, 2021). "Moreover, a decrease in IL-10+ γδ T lymphocytes was observed in lungs of OVA-induced asthma in mice." (PMID 33661375, 2021). "Indeed, a link was found between IL10 production, an anti-inflammatory cytokine, and Acinetobacter in asthma and atopic dermatitis." (PMID 32276591, 2020). "Therefore, further studies of the roles of IL-10 in asthma are required, taking in consideration, the impact and cross talk of other regulators, for better understanding of IL-10 roles in allergic asthma." (PMID 32024540, 2020). "IL-10 is a cytokine with key roles in immune regulation during asthma development." (PMID 33287119, 2020). "Acupuncture can remarkably decrease IL-6 and IL-10 in asthma patients." (PMID 33144870, 2020). "Kim showed the association of SNP in IL10 associated with patients with aspirin-intolerant asthma and rhinosinusitis with IL10-rs1800896 but not rs1800872." (PMID 31936183, 2020). "Levels of IL-12p40 and IL-3 during RSV infection in respiratory secretions, and persistence of VEGF, IFNγ, GCSF, IL-6, IL-7, IL-10, and IL-13 have also been speculated to serve as potential predictors for recurrent wheezing and/or asthma." (PMID 32357557, 2020). "Animal models of asthma showed that VDR-deficient asthmatic mice have significantly higher serum IgE levels, and vitamin D alongside VDR plays a role in decreasing IgE via the modulation of IL-10 secreting B cells." (PMID 32916790, 2020). "Furthermore in the context of asthma, we recently found that IL-10-producing ILC2s significantly dampened AHR and lung inflammation, together providing evidence of their regulatory role in the inflamed lungs." (PMID 33193309, 2020). "In addition, adoptive transfer of TGF-β and IL-10-treated DCs can significantly attenuated asthma presentation in sensitized mice." (PMID 32807859, 2020). "Additionally, studies have demonstrated that CD4+ Th2 cells, which play critical roles in asthma pathogenesis, are directly regulated by IL-10 during allergic airway inflammation." (PMID 33287119, 2020). "Importantly in the context of asthma, we recently found that IL-10–producing ILC2s significantly dampened AHR and lung inflammation, together providing evidence of their regulatory role in the inflamed lungs." (PMID 33193309, 2020).